INS (insulin)
Diseases named in the same sentence as INS in open-access papers (continued):
Sharing a sentence is not in itself a finding about the gene and the disease.
Insulin resistance (continued). "Insulin resistance may be another way that resistin interferes with tumorigenesis because resistin contributes to insulin resistance by interfering with insulin signaling pathways." (PMID 39184804, 2024). "Furthermore, EGCG has been found to reduce insulin resistance and improve insulin sensitivity by increasing insulin secretion." (PMID 39770980, 2024). "In Taylor’s hypothesis, ectopic fat deposition in the liver induces hepatic insulin resistance, decreases hepatic insulin clearance, and increases hepatic glucose production, thereby increasing the basal peripheral (posthepatic) plasma insulin levels." (PMID 39769002, 2024). "Under certain pathological conditions, the body's ability to utilize insulin to promote glucose metabolism is impaired, leading the body to produce excessive insulin to maintain stable blood glucose levels, a condition known as insulin resistance (IR)." (PMID 39537878, 2024). "However, with time, the β cells begin to fail, and insulin secretion cannot offset insulin resistance, leading to augmented plasma glucose levels and diabetes." (PMID 38693121, 2024). "Metabolic effects of SGLT2i have also been reported, independent of their glucuretic actions, which could improve insulin resistance, suppress insulin secretion by beta cells, and stimulate glucagon secretion by alpha cells of pancreatic islets." (PMID 38528542, 2024). "On the contrary, if the increase of insulin secretion cannot fully compensate for insulin resistance, DI index will decline, and abnormal SUA metabolism and HUA might occur." (PMID 38172728, 2024). "This can interfere with insulin signalling and lead to the development of insulin resistance." (PMID 39876919, 2024). "YO-T2D is secondary to both insulin resistance, in the liver, adipose tissue and peripheral tissues, and now increasingly recognized secondary to pancreatic β-cell dysfunction leading to reduced insulin production over time, and consequent relative insulin deficiency." (PMID 38958831, 2024). "Additionally, HFD AAV-USP13 mice had a reduced serum insulin levels and homeostasis model assessment of insulin resistance (HOMA-IR) compared to HFD AAV-GFP mice." (PMID 39033101, 2024). "Another impact of dexamethasone that contributes to the development of insulin resistance in rats is the downregulation of GLUT4, Insulin-Mediated Induction A signaling mechanism may cause insulin-regulated GLUT4 translocation." (PMID 39759349, 2024). "In the current experiments, we demonstrated that induced insulin resistance evinced by a higher circulating insulin level, together with normoglycemia and in consequence creating higher HOMA-IR and lower LISI indexes, triggered by sucrose, are prevented by NAC administration." (PMID 38279215, 2024). "To further confirm whether the 12 h TNF-α/24 h hypoxia model of adipocyte inflammation/insulin resistance could be maintained as a long term model, we assessed the insulin stimulated glucose uptake at 48 h and 72 h." (PMID 39415617, 2024). "Metformin alone showed similar effects to combination therapy on menstrual frequency, weight control, hyperandrogenemia, and insulin resistance, although a greater reduction in testosterone levels and total area under curves of glucose and insulin was observed with combination therapy." (PMID 38675438, 2024). "The effect of vitamin D supplementation was assessed by measuring glycated haemoglobin (HbA1c), fasting blood sugar (FBS), postprandial blood sugar (PPBS), fasting insulin, and insulin resistance as Homeostasis Model Assessment of Insulin Resistance (HOMA-IR) at the baseline and after six months." (PMID 39463653, 2024). "Research consistently shows that consuming meals earlier in the day (8 a.m. to 7 p.m.)is notably more effective in reducing body weight, fasting glucose levels, and insulin resistance, enhancing insulin response, and decreasing ghrelin levels compared to eating later in the day (12 p.m. to 11 p.m.)." (PMID 39203828, 2024).
Insulin resistance (continued). "Thus, it is of significance to further elucidate the link between glucose, insulin, lipids, and dopamine with respect to cellular bioenergetic (hyperglycaemia, insulin resistance) dysfunction in mitochondria." (PMID 39767747, 2024). "Reports have suggested that individuals with insulin resistance and elevated insulin levels due to MetS might experience an increase in BMD51." (PMID 38523143, 2024). "In summary, leptin, TNF-α, and IL-6 may participate in progressive maternal insulin resistance in pregnancy, whereas the insulin sensitivity-enhancing effect of adiponectin diminishes as its maternal concentrations decrease." (PMID 39519203, 2024). "Research indicated that UPS is crucial in insulin resistance by regulating insulin signaling." (PMID 39188976, 2024). "SNTNL1 may also play a role in preventing insulin resistance by contributing to progesterone-dependent insulin sensitization via decreasing Ser phosphorylation of IRS." (PMID 38883605, 2024). "Insulin resistance impairs insulin secretion from pancreatic β-cells." (PMID 38397072, 2024). "Therefore, their treatment is needed for preventing or mitigating complications caused by hormone imbalance such as high blood glucose in diabetics due to insufficient insulin secretion or response and insulin resistance in people with obesity or NAFLD." (PMID 38504163, 2024). "Furthermore, IMD overexpression significantly decreased fasting serum insulin levels, insulin resistance, serum levels of triglycerides, total cholesterol, LDL-C, and increased serum HDL-C levels in HFD-fed IMDtg mice versus HFD-fed WT mice." (PMID 39338366, 2024). "In addition, individuals who are overweight or obese often experience insulin resistance and high levels of insulin." (PMID 38650991, 2024). "T2DM is defined by a decreased response to insulin, also known as insulin resistance." (PMID 39063971, 2024). "Insulin resistance can be assessed by a variety of metrics, such as fasting insulin levels, normoglycemic clamp method, and homeostasis model assessment-IR (HOMA-IR) in vivo, however, these metrics are not routinely measured in clinical practice, especially in nondiabetic patients." (PMID 38218859, 2024). "Overall, these results strengthen the hypothesis that reduced BVR-A protein levels impairs insulin signaling and mitochondrial bioenergetics leading to UPRmt activation, before overt insulin resistance, consistent with findings in GK rats and BVR−/− mice." (PMID 38843768, 2024). "Third, persistent hyperinsulinemia itself can induce central and peripheral insulin resistance; long-term or inappropriate use of high doses of insulin may lead to weight gain and fat accumulation, which can, in turn, increase IR and elevate the TyG index." (PMID 39003471, 2024). "However, in type II diabetes, the pancreas produces insulin, but there are different degrees of insulin resistance precipitated by the complex interaction of genetic factors and environmental factors." (PMID 39744134, 2024). "In addition to the impaired hippocampal insulin signaling observed in the AD rat model, they also exhibited whole-body insulin resistance and high hepatic glucose output." (PMID 39337316, 2024). "Despite a short infusion protocol of 5 h, physiological hydrocortisone concentrations of ∼400 nmol/L were sufficient to increase insulin and glucose concentrations and decrease glucose clearance, in keeping with induction of insulin resistance over this time frame." (PMID 39546623, 2024). "Inflammation can disrupt insulin signaling pathways, resulting in insulin resistance." (PMID 38273385, 2024). "Since insulin resistance is a critical pathophysiological factor in MASLD18, it is questionable whether insulin sensitive GDM subtypes show similar MASLD risk." (PMID 38918525, 2024). "In addition, the presence of insulin resistance impairs the ability of insulin to promote glucose uptake and utilization, leading to elevated blood glucose levels." (PMID 39229376, 2024).
Insulin resistance (continued). "Insulin resistance occurs when cells exhibit diminished responsiveness to insulin, leading to impaired insulin sensitivity due to a reduced response of insulin signaling to blood glucose levels, resulting in a diminished physiological effect of insulin in the body." (PMID 39337348, 2024). "Additionally, it has been established that insulin resistance and decreased insulin secretion are key parameters that contribute to the onset of DM36." (PMID 38324798, 2024). "Elevated insulin resistance was identified as the most substantial predictive factor for MASLD in individuals whether obese or lean, and, furthermore, serum insulin levels are strongly associated with ballooning and hepatic lobular inflammation." (PMID 38397999, 2024). "The essence of insulin resistance is decreased insulin sensitivity and insulin responsiveness." (PMID 39076779, 2024). "However, mice fed with HFD exhibited significant weight gain, and developed an increase in fasting glucose, basal insulin levels and plasma cholesterol, together with glucose intolerance and insulin resistance." (PMID 39605858, 2024). "Insulin resistance (IR) is a decrease in the sensitivity of insulin target cells or tissues to insulin, and a reduction in the efficiency of insulin in promoting glucose uptake, which results in these cells or tissues require large amounts of insulin to produce normal biological effects." (PMID 38962445, 2024). "Hepatic insulin resistance could be attributed to impaired insulin-stimulated IRS-1 and IRS-2 tyrosine phosphorylation, as these changes were associated with the activation of PKCε." (PMID 39769002, 2024). "Fourth, excessive and inappropriate use of insulin, which may result in hypoglycemia, can further induce insulin resistance by stimulating the secretion of counter-regulatory hormones, mainly glucagon, along with catecholamines, cortisol, and growth hormone." (PMID 39003471, 2024). "Notably, another study reported an association between serum leptin levels and hyper-fasting serum insulin levels, demonstrating the correlation between leptin levels and insulin resistance in PCOS patients." (PMID 39459443, 2024). "The increased palmitic acid may attenuate the insulin signalling pathway and promote insulin resistance through decreasing the function of the endoplasmic reticulum (ER) and mitochondria." (PMID 39703541, 2024). "In fact, as insulin induces liposynthesis and influences appetite and energy expenditure, it was also proposed that hyperinsulinemia and insulin resistance may primarily induce weight gain." (PMID 38649714, 2024). "Inositols are considered possible mediators of insulin signaling, and their insufficiency may contribute to insulin resistance, T2DM, and DM complications." (PMID 38241313, 2024). "Taken together, the higher plasma leucine and insulin concentrations could indicate some degree of systemic insulin resistance after the inactivity period." (PMID 38406891, 2024). "In addition, as T2DM progresses, patients often experience increased insulin resistance, which leads to reduced cell responses to insulin." (PMID 39633380, 2024). "In addition, GK rats gradually exhibit insulin resistance, moderate hyperglycemia and impaired insulin secretion as frequently observed in human T2DM." (PMID 39273348, 2024). "With skeletal muscles and WAT still experiencing HFD-induced insulin resistance, this may still trigger the pancreatic beta cells to release insulin." (PMID 38425436, 2024). "We speculated that insulin resistance is due to insulin dependent induction of PTEN protein that prevent further increases in PI3K signaling." (PMID 38978604, 2024). "Additionally, insulin resistance, dyslipidemia, fat accumulation in the liver and adipose tissue, and altered insulin secretion all contribute to the aggravation of MetS." (PMID 38292473, 2024). "As chromium acts as an insulin sensitizer, it can reverse insulin resistance." (PMID 38563024, 2024).
Insulin resistance (continued). "Therefore, there is a vital need to predict insulin secretion (to prevent or manage insulin resistance or T2DM) or insulin demand, in the case of T1DM." (PMID 38474713, 2024). "The results suggest that JNDX can improve insulin resistance and insulin sensitivity in T2DM rats." (PMID 38835663, 2024). "In this regard, it needs to be noted that S1P signaling through S1PR2 has been shown to interact with insulin signaling, and might participate in the development of insulin resistance in peripheral cells." (PMID 37794263, 2024). "Mechanistically, several mainstream or classical pathological mechanisms of insulin resistance have gained widespread recognition, including oxidative stress, inflammatory response, insulin signal disorder, endoplasmic reticulum stress, as well as mitochondrial dysfunction." (PMID 39749015, 2024). "Notably, uric acid was the only variable consistently related to all three insulin sensitivity indices, highlighting its potential role in the pathophysiology of insulin resistance in T1D." (PMID 39218890, 2024). "Insulin resistance occurs at the expense of impaired insulin signaling in peripheral tissues such as liver, muscle, and fat, and can be accelerated by the presence of obesity and accumulation of dysfunctional adipose tissues, followed by a compensatory increase in insulin secretion." (PMID 39519454, 2024). "Insulin resistance is often accompanied by excessive insulin production from pancreatic beta cells." (PMID 39768214, 2024). "In insulin resistance syndrom, the secretion of the insulin from the pancreas may be normal or even elevated due to the decreased negative feedback if the glucose level is not regulated to optimal concentrations." (PMID 38702370, 2024). "Reducing body fat improves tissue sensitivity to insulin, reducing insulin resistance." (PMID 39459431, 2024). "The infusion’s enhanced antioxidant capacity could further contribute to reducing hyperglycemia and improving insulin sensitivity in diabetic patients, as oxidative stress is known to exacerbate insulin resistance." (PMID 39768408, 2024). "During the healthy pregnancy, a series of physiological changes occurred in hormones, immunity, and metabolism to support the well-being of both mother and developing fetus Among these changes, a notable shift in insulin sensitivity, termed insulin resistance is observed." (PMID 38248846, 2024). "One of the major causes of dysfunctional immunity in T2DM patients is hyperglycemia, which derives from to both insufficient insulin action (insulin resistance) and impaired insulin production by the β cells of the pancreas, with consequent increased glucose levels in the blood." (PMID 39247900, 2024). "Insulin signaling pathway is inhibited and as a result of that process, insulin resistance occurs." (PMID 38671840, 2024). "However, the study supports that NADH/NAD+ elevation promotes liver insulin resistance as the indicator of insulin sensitivity, such as enhanced hepatic gluconeogenesis, is associated with the fasting condition." (PMID 39873003, 2024). "Our longitudinal study suggests that higher fasting plasma insulin and insulin resistance associates with smaller hippocampal tail volumes in non-diabetic first-episode psychosis patients." (PMID 39085221, 2024). "In addition, P20 rats exhibit a physiological condition of insulin resistance characterized by high plasma levels of glucose and insulin." (PMID 38875221, 2024). "The effects of a ketogenic diet (KD) on fasting serum glucose, the area under the curve (AUC) of oral glucose tolerance test (OGTT), fasting serum insulin, homeostatic model assessment of insulin resistance (HOMA-IR), and serum beta-hydroxybutyrate (BHB) concentrations in diabetic mice." (PMID 38198459, 2024). "Insulin and insulin resistance levels were greater in patients with the three FTO polymorphisms." (PMID 38674326, 2024).
Insulin resistance (continued). "Formononetin, derived from Pueraria Mirifica, has demonstrated in some animal and in vitro studies the ability to mimic the biological activity of estrogen, modulate the insulin signaling pathway, ameliorate insulin resistance, and regulate the secretion of ovarian hormones." (PMID 39421869, 2024). "It is postulated that elevated leptin concentrations may contribute to insulin resistance by interfering with insulin signaling pathways." (PMID 39683486, 2024). "IGFBP-2 is also related to insulin resistance but is regulated more slowly by insulin." (PMID 38928106, 2024). "They lie within multiple biological pathways, contributing to (at minimum) β-cell development, insulin secretion and obesity-related insulin resistance, indicating that obesity and impaired β-cell function both are large pathophysiological factors in youth-onset T2D." (PMID 38278947, 2024). "Pulsatile insulin secretion from pancreatic β-cells is altered during the progression from prediabetes to type 2 diabetes and contributes significantly to the pathogenesis of insulin resistance in a variety of circumstances." (PMID 38791525, 2024). "The development of insulin resistance can be induced not only by hyperglycemia but also by obesity, potentially through the promotion of chronic inflammation in adipose tissue and an increase in systemic insulin secretion." (PMID 38720279, 2024). "Interestingly, a study in human APOE ɛ4-targeted replacement mice has shown that both aging and peripheral insulin resistance induce impairment of brain insulin signaling." (PMID 39656485, 2024). "To examine whether PGA-K is effective against insulin resistance, we determined the levels of leptin and insulin in serum using ELISA." (PMID 38542720, 2024). "Estrogen and estradiol can enhance insulin sensitivity and reduce insulin resistance." (PMID 38566220, 2024). "In the current study, the KD induced nutritional ketosis by increasing the mean BHB concentration to 1.25 mM, and reduced the serum insulin concentration and HOMA-IR, confirming the inverse association between the blood ketone concentration and indices of insulin resistance." (PMID 38198459, 2024). "These include hyperinsulinemia (due to insulin resistance in T2DM or use of exogenous insulin) and increased levels of IGF-1 which stimulates cell proliferation and inhibits apoptosis, and hyperglycemia affecting intracellular metabolism and impairing the immune system." (PMID 38492115, 2024). "Obesity has also been linked to dysregulation of IGF levels, through either increased IGF production or down-regulation of IGF binding proteins due to obesity-induced prolonged insulin resistance and hyper-insulinemia (“insulin-IGF hypothesis”)." (PMID 38339282, 2024). "The primary objective was to investigate the relationship between NAFLD and BMD, insulin levels, and markers of subclinical inflammation, hypothesizing that patients with NAFLD exhibit lower BMD, possibly linked to insulin resistance and inflammation." (PMID 38846245, 2024). "Additionally, GL ameliorated palmitate-induced insulin resistance by enhancing insulin-stimulated glucose uptake, increasing the phosphorylation of protein kinase B (PKB/AKT), and restoring the translocation of GLUT4 from the cytoplasm to the membrane." (PMID 38611884, 2024). "Thus exogenous insulin administration, enhancement of insulin secretion, and improvement of dysfunctions in insulin signaling such as insulin resistance serve as the main approaches for diabetic therapy." (PMID 38751366, 2024). "However, in prediabetic conditions, there are higher insulin secretion, HbA1c, blood glucose concentration, and early insulin resistance levels than in normal glucose-tolerant conditions." (PMID 39590330, 2024). "Furthermore, the decrease in adiponectin during obesity contributes to insulin resistance, due to the insulin-sensitizing role of adiponectin." (PMID 38892574, 2024).